MTOR (mechanistic target of rapamycin kinase)
Diseases named in the same sentence as MTOR in open-access papers (continued):
Sharing a sentence is not in itself a finding about the gene and the disease.
cancer (continued). "Interestingly, the inhibition of the PI3K-Akt-mTOR signaling pathway with a PI3K and mTOR dual inhibitor (NVP-BEZ235) was shown to be effective in reducing viable HER2-driven cancer cells." (PMID 26375550, 2015). "More recently we have demonstrated important differences between K7M2 and K12 in terms of the cancer stem cell factors mammalian target of rapamycin (mTOR), Notch1, and aldehyde dehydrogenase (ALDH1)." (PMID 25785263, 2015). "mTOR is a serine/threonine protein kinase and a key integrator of phosphatidyl-inositol-3 kinase (RTK-PI3K) pathways known to regulate cell growth, proliferation, and survival in human cancer cells." (PMID 25286393, 2014). "In addition, top three canonical pathways related to the gene sets are molecular mechanisms of cancer, LPS-stimulated MAPK signaling, IL-6 signaling, iNOS signaling, EIF2 signaling and mTOR signaling." (PMID 24416147, 2014). "Alternatively or in addition, low TRP levels may be sensed by the signaling complex mammalian target of rapamycin (mTOR), which may provide a TRP sufficiency signal not only in cancer cells but also in T cells." (PMID 25628622, 2014). "Several mTOR inhibitors have already gone through clinical trials for treating various cancers without great success." (PMID 24393708, 2014). "We demonstrate that dual pathway inhibition of the MAPK and PI3K/AKT/mTOR pathway synergistically reduces cell viability in NRAS mutant cancers regardless of their tissue origin." (PMID 25277205, 2014). "For example, in phase 1 clinical trials, patients with PIK3CA-aberrant cancer had a higher clinical response rate to treatment with PI3K/AKT/mTOR inhibitors than patients who lacked these aberrations." (PMID 25593991, 2014). "Thus dysregulated AKT/mTOR pathway can promote SREBP expression and activity which in turn enhances cancer cell lipid biosynthesis." (PMID 25505994, 2014). "It has been reported that Notch is a positive regulator of the PI3K/AKT/mTOR pathway in T-ALL suggesting that mTOR and Notch may cooperate in a shared regulatory loop to influence cancer cell differentiation or proliferation in a dose dependent manner." (PMID 25566499, 2014). "One of the most frequently activated signaling cascade in cancer is the PI3-K/Akt/mTOR pathway, which is not only involved in cell survival and invasion, but also in proliferation, DNA damage repair and cell growth/metabolic regulation." (PMID 24595238, 2014). "Further downstream signalling is very complex that is understood by the fact that therapeutic regimens that target only mTOR are not very effective to treat cancer." (PMID 25505994, 2014). "The anti-cancer effects of metformin may probably involve the activation of the AMPK, inhibition of the mTOR pathway, and inhibition of insulin-like growth factors." (PMID 25303400, 2014). "As an important part of PI3K/Akt pathway which is critical to cancer development, mTOR was aberrantly activated in most if not all human carcinogenesis." (PMID 24804240, 2014). "Metformin mediates mammalian target of rapamycin (mTOR) pathway via the activation of AMPK and tuberous sclerosis complex 2 (TSC2), phosphorylation of TSC2 which leads to an inhibition of mTOR signaling and reduction in protein synthesis for cancer cells." (PMID 24647047, 2014). "Previous studies in other cancer cell types indicated that limited or absent inhibition of phosphorylation of 4EBPs was the main cause of resistance to rapalogs and that this resistance could be eliminated by new generation inhibitors targeting the kinase activity of mTOR." (PMID 25026292, 2014). "Furthermore, the practice of targeted cancer therapy combinations have demonstrated the benefits of co-targeting closely related molecular targets, especially in the MAPK and the PI3K/Akt/mTOR pathways." (PMID 24713621, 2014).
cancer (continued). "We also compared the effect of red wine with that of the mTOR inhibitor rapamycin and the anti-diabetic drug metformin, both of which inhibit signaling events downstream of PI3K and are under investigation as promising therapeutics in cancer." (PMID 24456610, 2014). "The PI3K/Akt/mTOR pathway has been shown to be upregulated in CCA cells and this pathway may be a suitable target for the effective treatment of this cancer." (PMID 24527093, 2014). "The functional analysis using IPA shows that the genes from our pipeline were involved in canonical pathways such as molecular mechanisms of cancer, IL-6 signaling, LPS-stimulated MAPK signaling pathways, iNOS Signaling, EIF2 signaling and mTOR signaling pathways." (PMID 24416147, 2014). "However, LPAAT-β is now being studied as an important regulator of cell growth and differentiation and as a potential therapeutic target in cancer since PA is necessary for the activity of key proteins such as Raf, PKC-ζ and mTOR." (PMID 24205284, 2013). "SFN is reported to inhibit Akt/mTor and MEK/ERK/pathways in cancer cells." (PMID 23927827, 2013). "Phosphorylation sites on 4EBP1 (gene name EIF4EBP1) or Ribosomal S6 (gene name RPS6), which are known to be downstream of PI3K/mTOR, did not correlate with the responses of our cancer cell panel to the PI3K/mTOR inhibitor PI-103." (PMID 23628362, 2013). "mTOR inhibition became an active area of research to develop and test small inhibitory molecules such as rapamycin analogues -notably RAD001 (Everolimus, Novartis) and CCI-779 (Torisol, Wyeth) to treat diverse diseases, including cancer." (PMID 23799002, 2013). "The activity of ALDH in cancer may function to neutralize oxidative stress and provide chemoresistance, and thus upregulation of ALDH activity by mTOR may be one mechanism that confers resistance to oxidative stress in K7M2 cells." (PMID 23476113, 2013). "Although Akt inhibition leads to mTORC1 inhibition and its inhibition promotes autophagy, it has been shown in cancer cells that subsequent downstream signaling of Akt can contribute to autophagic regulation independent of mTOR." (PMID 23894332, 2013). "The mammalian target of rapamycin (mTOR), is a downstream conduit of EGFR and MET signaling, and is thus considered a therapeutically attractive target in the treatment of various types of cancers." (PMID 23690929, 2013). "There is ongoing interest in the mechanism of action of the antagonistic action of rapamycin on mTOR signalling, not least due to its anti-cell growth/cancer drug potential." (PMID 23311891, 2013). "In this sense, reduction in the protein synthesis rate in a cell is of great importance in respect of cancer therapy, and this is beautifully demonstrated in APC mutant mice in which inhibition of mTOR drastically suppressed intestinal polyp formation and reduced mortality." (PMID 23592547, 2013). "In addition, there are various signaling cascades that regulate mTOR including the HER2/PI3K (class I) pathway; inhibition of HER2/PI3K (class I) pathway has been shown to induce autophagy in cancer." (PMID 23843890, 2013). "Thus, mTOR inhibitors achieve growth inhibition by suppressing both survival signals from EGFR and resistance signals from MET in cancer cells." (PMID 23690929, 2013). "Moreover, the effects of the inhibition of the PI3K/Akt/mTOR pathway can be circumvented in cancer cells through the Raf/MEK/ERK signaling system, which may protect malignant cells from drug-induced proapoptotic injuries and, therefore, produce chemoresistant cancer cells variants." (PMID 24381788, 2013). "Although several mTOR pathway components have been investigated in a number of cancers including those of the colon, to our knowledge, no study investigating their expression in patient-derived CoCSCs has been reported so far." (PMID 24185040, 2013). "The strategy of combining both miRNAs and mTOR inhibitors has not been studied extensively in cancer research." (PMID 23434669, 2013).
cancer (continued). "Inhibition of multiple components of the PI3K-AKT-mTOR axis in cancer cells is particularly attractive as mTOR exerts negative feedback regulation on AKT1 as demonstrated by the limited efficacy of rapamycin or its analogs." (PMID 23863691, 2013). "The mTOR/Raptor pathway is thought to suppress ULK1 and ULK2 and their regulatory subunits, while AMPK phosphorylates ULK1, leading to autophagy-mediated cancer cell death." (PMID 23875169, 2013). "Several mTOR inhibitors, including Rapamycin, have already gone through clinical trials as single agents for treating various cancers without great success." (PMID 24185040, 2013). "As opposed to its cancer promoting effects via other signalling pathways, in this particular system, mTOR acts to reduce cancer." (PMID 24400038, 2013). "mTOR is a master regulator of protein synthesis and, therefore, the selectivity of mTOR inhibitors against cancer cells with high protein synthesis rates is not surprising." (PMID 24279929, 2013). "Very interestingly, in our cancer cells, AKT activation related to PARP1 inhibition was unable to modulate pro-survival signals, probably because the downstream pathway was interrupted at the level of its effector mTOR." (PMID 23301673, 2013). "Another frequent genetic event occurring in human cancer is loss of function of the tumor suppressor PTEN, which normally suppresses activation of the PI3K/Akt/mTOR pathway by functioning as a lipid phosphatase." (PMID 22545054, 2012). "mTOR is an important signal transducer downstream of the PI3K/AKT pathway that mediates the effects of multiple growth factors, is up-regulated and highly active in multiple cancers including those of the colon, and is a drug target for cancer therapeutics." (PMID 23056418, 2012). "The major limitation for the development of mTOR inhibition therapy is the absence of predictive biomarkers of efficacy and its resistance mechanisms in cancer." (PMID 22408430, 2012). "A recent study of human cancer cell lines showed that ZSTK474 has potent effects on arrest of cell cycle progression through inhibition of phosphorylation or expression of Akt and/or mTORC1 substrates, such as p-GSK3β, p-mTOR, p-p70S6K and cyclin D1." (PMID 22647622, 2012). "PI3K/AKT/mTOR and RAS/RAF/MEK/ERK pathways are thought to be the central transducers of oncogenic signals in solid malignancies, and there has been a lot of enthusiasm for developing inhibitors of these pathways for cancer therapy." (PMID 23259591, 2012). "In addition to mediating growth factor signaling and metabolism in the growth and proliferation of a variety of normal and cancer cell types, the AKT/mTOR pathway is known to facilitate survival and protect against apoptosis." (PMID 22680924, 2012). "Rapalog mTOR inhibitors are known to induce IRS-1-mediated, upstream feedback activation of PI3K-AKT, which is thought to be important for the limited clinical efficiency of the therapy for most cancers, including NSCLC." (PMID 23259591, 2012). "It has been documented that STAT3 gene expression is regulated by mTOR signaling in cancer cells, however, it is not clear why the addition of clofarabine to temsirolimus resulted in further down-regulation of STAT3 gene." (PMID 23271044, 2012). "In these cancers, RET activates the ERK/MAPK, the PI3K/AKT/mTOR and the JAK/STAT3 pathways." (PMID 23056499, 2012). "For example, the dual PI3K/mTOR inhibitor NVP-BEZ235 (Novartis) is an orally bioavailable reagent that was reported to inhibit tumor growth in many preclinical models, and it enhanced the antitumor activity of several other cancer drugs." (PMID 22680924, 2012).
cancer (continued). "Metformin negatively regulates mammalian target of rapamycin (mTOR) complex 1 (mTORC1) and the crosstalk between insulin/IGF-1 receptor and G-protein coupled receptor (GPCR) signaling, thus inhabiting the development of certain types of cancer." (PMID 22920886, 2012). "Collectively the findings in the present study suggest that quercetin inhibits tumor growth and angiogenesis by targeting VEGF-R2 regulated AKT/mTOR/P70S6K signaling pathway, and could be used as a potential drug candidate for cancer therapy." (PMID 23094058, 2012). "Moreover, while the treatment of PET cells with mTOR inhibitor triggered a prosurvival response dependent on PI3K/AKT signaling in PET cells, as also shown in other types of cancer, the simultaneous inhibition of SFKs blocked this escape signal." (PMID 23344019, 2012). "Such inhibitor compounds will serve as chemical biology tools for pharmacological target validation in terms of Mnk's role in regulation of Raf/MEK/ERK, PI3K/PTEN/Akt/mTOR and Jak/STAT pathways in cancers, as well as their functions required for normal physiological process." (PMID 22392765, 2012). "Surprisingly, non-transformed cell lines were not less sensitive to rapamycin and did not have lower eIF4E activities than cancer lines, suggesting the mTOR/4E-BP1/eIF4E axis is deregulated in these non-transformed cells." (PMID 21320304, 2011). "These protein kinases are also hypothesized to regulate other cancer pathways such as MAPK, JNK, NF-κB, mTOR and the focal adhesion pathway." (PMID 21552547, 2011). "Other genes with known roles in cancer included Smoothened, a G-protein coupled receptor in the hedgehog pathway; the transcriptional activator Eya2; the histone-binding oncoprotein SET; and the mTOR inhibitor Depdc6." (PMID 21559491, 2011). "The mTOR inhibitors CCI-779 and everolimus (RAD001) have already been approved for treatment of advanced renal cancer; together with other mTOR inhibitors, they are under clinical investigation for several other cancer indications." (PMID 20683448, 2010). "While early indications from transplant registry data, and from studies not directed at determining tumour development, suggest a general decrease in cancer with mTOR inhibitors, no prospective randomised data has yet confirmed this idea." (PMID 20459775, 2010). "Transfection with a non-targeting siRNA (both Akt and mTOR) did not sensitize cancer cells to CDDO-Me (not shown)." (PMID 21799944, 2010). "Responses in clinical trials using mTOR inhibitors have been sporadic and not necessarily predicted by cancer histology." (PMID 20543980, 2010). "Other signaling systems that directly affect to GLUT expression may be also altered in cancer, such as the PI3K/Akt/mTOR pathway which conveys the signal from insulin to cell." (PMID 20706540, 2010). "It is made of an antimetabolite (NSC174121, methotrexate derivative), a mTOR inhibitor (NSC606698, rapamycin) and a compound of unknown mechanism of action (NSC671526), where NSC stands for cancer chemotherapy National Service Center number." (PMID 19660129, 2009). "As mTOR signalling is dependent on growth factors, including EGF, we compared everolimus with gefitinib or cetuximab in both wild type and EGFR inhibitor-resistant cancer cell lines, focusing on the mTOR effector p70S6 Kinase." (PMID 18319715, 2008). "Indeed, many cancers have increased expression of enzymes that are inhibited by AMPK, such as FAS and mTOR." (PMID 17623090, 2007). "Our data suggests an explanation for the anti-tumor activity of mTOR inhibition in a clinical trial of RCC, especially in those RCCs with PTEN alterations, and these data support further trials of mTOR inhibitors in RCC and other HIF-activated cancers." (PMID 17300726, 2007). "Inhibition of mTOR by rapamycin has been standard treatment for immunosuppression following organ transplant, and the rapamycin derivative CCI-779 is now being clinically tested as a cancer chemotherapy." (PMID 16255777, 2005).
cancer (continued). "In cancer models, cannabinoids have been shown to enhance the cytotoxic efficacy of conventional chemotherapeutics (e.g., cisplatin, 5-fluorouracil, and doxorubicin) by promoting oxidative stress, inhibiting the PI3K/AKT/mTOR signaling pathway, and amplifying autophagy-mediated apoptosis." (PMID 41516397, 2026). "Consequently, rapamycin treatment did not improve its phenotype, suggesting that mTOR signaling is not a primary driver of cancer-related features in FAP2." (PMID 40702333, 2025). "Additionally, the discovery of synthetic lethality involving Wnt signaling suggests that CTNNB1-mutant cancers may be vulnerable to combination therapies targeting other pathways that intersect with Wnt signaling, such as the PI3K/AKT/mTOR pathway." (PMID 40072110, 2025). "However, in cancer cells, the reduction in ATP caused by FAO inhibition does not activate mTOR but instead induces autophagy, leading to anticancer effects." (PMID 40848971, 2025). "Metformin may directly inhibit pathway related to cancer invasion and migration, including AMP-activated protein kinase (AMPK), epithelial-mesenchymal transition (EMT), VEGF and mammalian target of rapamycin (mTOR), thus inhibiting cancer cell progression." (PMID 40191722, 2025). "Additionally, we discovered that LINC00261 acts as a molecular sponge for miRNAs, such as miR-550a-3p, miR-23a-3p, miR-148a, miR-324-3p, and miR-105-5p, regulating critical cancer-related signaling pathways, including PI3K/Akt/mTOR, Protein kinase B, and Mammalian target of rapamycin (mTOR)." (PMID 40136629, 2025). "They show that DGKH dependent production of PA ignites mTOR activity independently of the canonical phosphatidylinositol 3-kinase-protein kinase B (PI3K-AKT) axis, thereby forging a direct mechanistic link between lipid signaling, cancer stem-cell traits and sustained mTOR activation." (PMID 41323031, 2025). "While most of the mTOR inhibitors have not achieved their primary endpoints in cancer clinical trials, they offer promising drug repurposing opportunities in the treatment of non-cancer diseases, as they have already undergone safety and tolerability evaluations and are ready for clinical use." (PMID 40299431, 2025). "Additionally, phosphorylated mTOR (p‐mTOR) levels did not change with β‐Lap treatment alone or in combination with CGA in any of the cancer cells, despite the reduction in p‐mTOR levels induced by the mTOR inhibitor rapamycin." (PMID 40014262, 2025). "Several mTOR inhibitors, including sirolimus, temsirolimus, and everolimus, are approved for clinical application as immunosuppressive agents in organ transplant recipients and as noncytotoxic agents for the treatment of certain cancers." (PMID 40392604, 2025). "Indeed, mTOR and AMPK are regarded as metabolic sensors that relay cell survival signals under stress, and such crosstalk with mitochondrial function and telomere maintenance is essential for promoting cancer." (PMID 40149420, 2025). "Thus, by modulating the mTOR pathway, inducing autophagic degradation of YAP, and inhibiting the Wnt/β-catenin signaling pathway, silibinin suppresses tumor growth and metastasis in various cancers." (PMID 40490812, 2025). "Although, inhibition of mTOR may help in protecting the cancer cells, one should also keep in mind the negative effects of the same." (PMID 38584538, 2025). "Previous studies have demonstrated that baicalein inhibits cancer cell proliferation by upregulating the expression of DNA-Damage-Inducible Transcript 4 (DDIT4), which in turn suppresses the phosphoinositide 3-kinase/protein kinase B/mammalian target of rapamycin (PI3K/AKT/mTOR) signaling pathway." (PMID 41303544, 2025). "Notably, p-S6Ser235/236 expression was also downregulated in mortalin-knockdown cells, suggesting that mortalin acts as an upstream regulator of Akt/mTOR signaling, which promotes proliferation, migration, EMT, invasion, and angiogenesis, while inhibiting autophagy in cancer cells." (PMID 40940957, 2025).